CDC45 (cell division cycle 45)
Description:
Required for initiation of chromosomal DNA replication. Core component of CDC45-MCM-GINS (CMG) helicase, the molecular machine that unwinds template DNA during replication, and around which the replisome is built.
Synonyms: CDC45L; CDC45L2; MGORS7; PORC-PI-1
Tractability: Small molecule: a structure with a bound ligand is known. PROTAC: ubiquitination databases record sites on it; a small molecule that binds it is known.
Target class: Other nuclear protein
Gene: Protein-coding gene on chromosome 22 (19,479,457 to 19,520,612, forward strand). Ensembl gene ENSG00000093009.
Subcellular location: Nucleus; Chromosome
Subcellular location (Human Protein Atlas): Nucleoplasm; Centrosome; Cytosol
Pathways (Reactome):
Cell Cycle: Activation of ATR in response to replication stress; G1/S-Specific Transcription
DNA Replication: Activation of the pre-replicative complex; Unwinding of DNA
Gene Ontology:
Molecular function: protein binding; chromatin binding; DNA replication origin binding; single-stranded DNA binding
Biological process: DNA replication; DNA replication checkpoint signaling; DNA replication initiation; double-strand break repair via break-induced replication; mitotic DNA replication preinitiation complex assembly
Cellular component: ciliary basal body; CMG complex; cytosol; nucleoplasm; nucleus; DNA replication preinitiation complex; chromosome
Genetic constraint (gnomAD): Loss-of-function variants: 41 observed, 69.08 expected, observed/expected ratio (o/e) 0.59, 90% interval 0.46 to 0.77. The upper end of that interval is the gene's LOEUF score, 0.77, which puts it in group 3 of 6, group 1 being the genes least tolerant of losing a copy. Missense variants: 571 observed, 671.75 expected, observed/expected ratio (o/e) 0.85, 90% interval 0.79 to 0.91. Synonymous variants: 228 observed, 256.54 expected, observed/expected ratio (o/e) 0.89, 90% interval 0.8 to 0.99.
Gene-disease validity (ClinGen):
ClinGen rates the evidence that CDC45 causes each of these diseases.
Meier-Gorlin syndrome 7 (autosomal recessive): Definitive.
Homologues: Orthologues: macaque CDC45 (98% identical), dog CDC45 (93% identical), pig CDC45 (93% identical), guinea pig CDC45 (92% identical), mouse Cdc45 (92% identical), chimpanzee CDC45 (91% identical), rat Cdc45 (86% identical), tropical clawed frog cdc45 (79% identical), zebrafish cdc45 (74% identical), Drosophila melanogaster Cdc45 (39% identical), Caenorhabditis elegans evl-18 (29% identical).
Diseases named in the same sentence as CDC45 in open-access papers:
CDC45 is named in the same sentence as 64 diseases in open-access papers, as found by Europe PMC text mining. Sharing a sentence is not in itself a finding about the gene and the disease. The quoted sentences say what the papers report.
lung cancer (9 papers, 2020 to 2024). A malignant neoplasm involving the lung. "Knockdown of CDC45 not only suppressed the proliferation and migration abilities of lung cancer cells but also caused cell cycle arrest at the G2/M phase." (PMID 38589907, 2024). "CDC45-deficient lung cancer cells exhibited cell cycle arrest, leading to the inhibition of stemness and metastasis." (PMID 38589907, 2024). "As a novel regulator of stemness, CDC45 plays a role in regulating lung cancer cell proliferation, migration, and cell cycle." (PMID 38589907, 2024). "Then, in vitro, experiments such as colony formation assay, scratch assay, and transwell assay were conducted to evaluate the impact of CDC45 knockdown on the proliferation and migration abilities of lung cancer cells." (PMID 38589907, 2024). "Previous studies of solid tumors such as CRC, breast, and lung cancers have discovered increased levels of expression of CDC45, which stimulate the multiplication of cells." (PMID 38485838, 2024). "Previously, the similar approach was utilized in Cdc45, demonstrating that strongly immunogenic Cdc45‐derived peptides stimulated CTLs to be reactive to lung cancer cells." (PMID 36776764, 2023). "Upregulated expression of Cdc45 is also a predictor for multiple cancers, including breast cancer, leukemia, lung cancer and osteosarcoma." (PMID 36776764, 2023). "Studies show that CDC45 overexpression is involved in colorectal, papillary thyroid and non‐small cell lung cancer initiation and progression." (PMID 35810383, 2022). "It had been reported that CDC45 was commonly highly expressed in various malignant tumors such as breast cancer, cervical cancer, lung cancer, and glioblastoma, and that CDC45 may be a marker for the proliferation of various malignant tumors." (PMID 37642814, 2024). "With further research on CDC45, it has been discovered that its expression level is closely related to disease progression in malignant squamous cell carcinoma, cervical cancer, prostate cancer, and lung cancer." (PMID 38589907, 2024). "Finally, in vivo model with subcutaneous injection of lung cancer cells was performed to verify the effect of CDC45 on tumor growth." (PMID 38589907, 2024). "It has been reported that CDC45 overexpression was observed in lung cancer and was considered a novel tumour-associated antigen (TAA) that might be a useful target for lung cancer immunotherapy." (PMID 33614286, 2021). "The largest increase in CDC45 loading was seen for the combined treatment, but even if this increase was similar in all cell lines very little DNA damage induction was observed in three of the lung cancer cell lines." (PMID 34359691, 2021). "EPIC1 downregulation decrease the expression of Cyclin A1, Cdc20, and Cdc45 in lung cancer cells." (PMID 32322669, 2020). "Therefore, CDC45 may serve as a potential target for lung cancer treatment and provide a reference for further mechanistic research and therapeutic development." (PMID 38589907, 2024). "Considering the functional characteristics of CDC20, CDC45, TRIM37 and MMP9, it is not surprising that BARX1 promotes cellular proliferation, migration and invasion of lung cancer cells by transactivating CDC20, CDC45, TRIM37 and MMP-9 expression." (PMID 37587140, 2023). "We therefore conclude that BARX1 transactivates CDC20, CDC45, TRIM37 and MMP-9 genes, thereby promoting cellular proliferation, migration and invasion of lung cancer cells due to the functional roles of these genes in cell-cycle progression, DNA synthesis and their association with carcinogenesis." (PMID 37587140, 2023). "To investigate potential mechanisms behind why lung cancer cell lines lacked a synergistic induction of S-phase DNA damage, we asked whether drug-induced loading of CDC45 might be defective." (PMID 34359691, 2021).
colorectal cancer (8 papers, 2013 to 2024). A primary or metastatic malignant neoplasm that affects the colon or rectum. "CDC45 was reported to be a potential prognostic and diagnostic biomarker in colorectal cancer (CRC) and HCC, but few mechanisms have been found." (PMID 35360870, 2022). "Moreover, previous studies have identified CDC45 as a proliferation-associated antigen and have shown its close association with the progression of various cancers, including cervical cancer, colorectal cancer, acute myeloid leukemia], and ovarian cancer." (PMID 38589907, 2024). "Intriguingly, patients with lower CDC45 expression exhibited a more unfavorable survival prognosis in GC, consistent with findings in colorectal cancer, cervical squamous cell carcinoma and endocervical adenocarcinoma." (PMID 38515458, 2024). "As the gene with the smallest p-value in the cell cycle G1/S transition gene set, CDC45 encodes cell division control protein 45 and has been linked to many cancers according to its expression, including HCC and colorectal cancer." (PMID 32393195, 2020).
craniosynostosis (7 papers, 2017 to 2024). Craniosynostosis is defined as the premature fusion of one or more cranial sutures leading to secondary distortion of skull shape resulting in skull deformities with a variable presentation. "Here we have identified a second cohort of families segregating CDC45 variants, where patients have craniosynostosis and a reduction in height, alongside common facial dysmorphisms, including thin eyebrows, consistent with MGORS7." (PMID 38467731, 2024). "We note interesting observations arising across this group of genes as the number of patients has increased, such as the unusually high number of synonymous variants affecting splicing in CDC45 and a subgroup of genes that also cause craniosynostosis." (PMID 37059840, 2023). "The strong association of craniosynostosis with CDC45 variants supports the use of this feature as a differential diagnosis in genetic testing." (PMID 37059840, 2023). "As the number of genes associated with MGORS increases, we see the appearance of subtypes, notably the prevalence of craniosynostosis in CDC45-associated MGORS and neutropenia in GINS3-associated MGORS." (PMID 37059840, 2023). "Variants in CDC45 underlie a MGORS subtype clinically characterised by the very common appearance of craniosynostosis." (PMID 37059840, 2023). "Investigation of the remaining allele in our tested cohort revealed a rare nonsynonymous damaging variant in CDC45 in one patient out of eight with craniosynostosis." (PMID 36980952, 2023). "Craniosynostosis was present in many of the individuals with CDC45 variants but is an incompletely penetrant trait (13/14 individuals), as observed by the discordance of bicoronal craniosynostosis in two affected brothers." (PMID 37059840, 2023). "Our patient’s phenotype is strikingly similar to the phenotype of individuals with CDC45 variants, particularly those who presented with craniosynostosis and mild MGORS features." (PMID 34353863, 2022). "However, investigation of the remaining allele in our tested cohort revealed a rare nonsynonymous-damaging variant in CDC45 in one patient out of 8 with craniosynostosis." (PMID 36980952, 2023). "For example, biallelic mutations in CDC45 are thought to be the cause of craniosynostosis in Meier–Gorlin syndrome (MGORS7, OMIM 617063), a rare autosomal recessive primordial dwarfism disorder, characterized by microtia, short stature, and absent or hypoplastic patellae." (PMID 36980952, 2023). "Biallelic variants in CDC45 are associated with a distinct spectrum of clinical features designated as MGORS7 (MIM 617063); while craniosynostosis is almost always present, many patients also have microtia and patella hypo/aplasia, more typical of MGORS." (PMID 38467731, 2024). "Previously, hypomorphic variants in genes involved in the regulation of cell division, including CDC45 and RECQL4 (both Green genes) were reported in patients with craniosynostosis." (PMID 36980886, 2023). "In addition to the characteristic triad, this patient has many features in common with the CDC45-MGORS subtype, such as craniosynostosis, atrial septal defect, and an anteriorly placed anus." (PMID 37059840, 2023). "Interestingly, our patient’s phenotype is strikingly similar to the phenotype of patients with CDC45-related MGORS, particularly those with craniosynostosis, mild short stature and patellar hypoplasia." (PMID 34353863, 2022). "To date, biallelic CDC45 variants have been reported in 19 individuals across 15 families and underlie a broad spectrum of phenotypes that range from a classic MGORS presentation to syndromic craniosynostosis with short stature but no other MGORS features." (PMID 37059840, 2023).
Meier-Gorlin syndrome (7 papers, 2017 to 2024). "CDC45 is part of the helicase complex responsible for DNA unwinding during DNA replication and CDC45 mutations, including the R157C mutation, have been associated with Meier-Gorlin syndrome, a developmental condition characterised by short stature." (PMID 39009827, 2024). "This is highlighted by the newly discovered interaction between CDC45 and KPNA7, for which we demonstrated that the R157C CDC45 mutation, associated with Meier-Gorlin syndrome, disrupts KPNA7 binding and results in the delocalisation of CDC45 from the nucleus." (PMID 39009827, 2024). "However, many clinical manifestations of W030 matched Meier-gorlin syndrome, a disease caused by CDC45." (PMID 36118902, 2022). "Finally, we show that a Cdc45 mutation found in patients with Meier-Gorlin syndrome disrupts the functional interaction with Rad53 in yeast." (PMID 30595439, 2019). "Additionally, mutations in key components involved in initiation of DNA replication, such as ORC1, ORC4, ORC6, CDT1, CDT6, and CDC45, have been reported to be the cause of Meier-Gorlin syndrome, a primordial dwarfism syndrome." (PMID 28915237, 2017). "Among the interactions, we uncover a novel nuclear localisation signal (NLS) in the Cell division control protein 45 (CDC45) that binds importin subunit α-8 (KPNA7), and is disrupted by a R157C mutation associated with a developmental disorder called Meier-Gorlin syndrome." (PMID 39009827, 2024). "Meier-Gorlin syndrome (MGS) is caused by mutations in components of the prereplication and pre-initiation DNA replication complexes (ORC1, ORC4, ORC6, CDT1, CDC6, GMNN, CDC45), which license replication origins and mediate loading and functioning of the replication fork helicase." (PMID 28630177, 2017).
papillary thyroid cancer (7 papers, 2021 to 2024). "In line with this, the silencing of CDC45 in papillary thyroid cancer cells resulted in identical tumor compromising effects." (PMID 36077733, 2022). "CDC45 might also promote papillary thyroid cancer progression and nasopharyngeal carcinoma." (PMID 35149954, 2022). "Moreover, CDC45 has previously been identified as a candidate oncogene in non-small cell lung cancer, hepatocellular carcinoma, papillary thyroid cancer, and cervical cancer; however, the expression profile and function of CDC45 in HNSCC have rarely been reported." (PMID 33982750, 2021).
glioma (6 papers, 2019 to 2024). A benign or malignant brain and spinal cord tumor that arises from glial cells (astrocytes, oligodendrocytes, ependymal cells). "It is reported that the poor prognosis of glioma patients was highly linked with the upregulation of circ-CDC45 in glioma samples, because circ-CDC45 had the oncogenic functions of promoting glioma progression." (PMID 38075205, 2024). "For example, the regulatory network of circ-CDC45/miR-527 has a crucial effect on the proliferation and invasion of glioma cells." (PMID 33472586, 2021). "By sponging the antioncogene miR-527, circ-CDC45 facilitates glioma cell progression." (PMID 35210429, 2022). "Distribution of glioma cells expressing MCM2 and CDC45 which confer the helicase activity on GINS complex by forming a CMG complex was also examined." (PMID 30465075, 2019). "Frequency of MCM2- or CDC45-positive glioma cells was independent of their spatial relation to the ischemic necroses." (PMID 30465075, 2019). "In contrast, MCM2 and CDC45 were almost ubiquitously expressed, both inside and outside the peri-necrotic areas, in proliferating as well as non-proliferating glioma cells." (PMID 30465075, 2019).
melanoma (6 papers, 2008 to 2024). A malignant, usually aggressive tumor composed of atypical, neoplastic melanocytes. "To further elucidate the effects of CDC45 on melanoma phenotypes, we established the overexpression models of CDC45." (PMID 35620458, 2022). "Hsa_circ_0062270 promotes proliferative, migrative and invasive functions in melanoma cells via stabilizing the linear transcript CDC45." (PMID 35620458, 2022). "Hsa_circ_0062270 stimulated malignant process of melanoma by stabilizing its linear transcript CDC45." (PMID 35620458, 2022). "In melanoma cells overexpressing CDC45, EdU-positive rate increased." (PMID 35620458, 2022). "All above indicated that hsa_circ_0062270 may play a carcinogenic role in melanoma by stabilizing its linear transcription CDC45." (PMID 35620458, 2022). "Identically, CDC45 was highly expressed in melanoma cell lines." (PMID 35620458, 2022). "Overexpression of hsa_circ_0062270 could enhance the down-regulated CDC45 in melanoma cells transfected with si-CDC45." (PMID 35620458, 2022). "Knockdown of CDC45 blocked proliferative, migratory and invasive functions of melanoma cells, which could be reversed by overexpression of hsa_circ_0062270." (PMID 35620458, 2022). "Hsa_circ_0062270 could stabilize the expression of linear transcript CDC45, and thus participated in the malignant process of melanoma." (PMID 35620458, 2022). "Moreover, migratory and invasive potentials of melanoma were promoted by overexpressed CDC45." (PMID 35620458, 2022). "Therefore, CDC45 could stimulate the malignant process of melanoma." (PMID 35620458, 2022).
non-small cell lung carcinoma (6 papers, 2021 to 2024). A group of at least three distinct histological types of lung cancer, including non-small cell squamous cell carcinoma, adenocarcinoma, and large cell carcinoma. "This study aimed to assess the functions of cell division cycle protein 45 (CDC45) in Non-small cell lung cancer (NSCLC) cancer and its effects on stemness and metastasis." (PMID 38589907, 2024). "Ultimately, we validated that high expression of CDC45 promotes tumor stemness and lymph node metastasis in non-small cell lung cancer by regulating the cell cycle." (PMID 38589907, 2024). "CDC45 is a component of the cell division cycle 45 (CDC45) minichromosome maintenance protein complex (MCM) and has been reported to be upregulated and identified as a hub gene in non-small-cell lung cancer." (PMID 35149954, 2022). "CDC45 acts as a hubprotein, significantly upregulated in cancerous tissues from CRC and non-small-cell lung cancer (NSCLC) patients, and promotes tumor progression." (PMID 33564675, 2021).
breast carcinoma (4 papers, 2020 to 2024). "In breast cancer and colon cancer, POLQ is associated with the upregulation of genome stability genes and replication initiation proteins such as CDC6, CDT1, and CDC45." (PMID 38270643, 2024). "We were able to validate multiple correlations with DEK expression and both down- and up-regulated genes in primary human breast cancers, including CCL5, CDC45, CDH1, and HDAC7." (PMID 32708944, 2020).
cervical cancer (4 papers, 2021 to 2024). A primary or metastatic malignant neoplasm involving the cervix. "Furthermore, previous studies have also found that CDC45 was indeed associated with prognosis in cervical cancer, which strongly demonstrates the reliability of our results." (PMID 34557356, 2021). "The results showed that the CDC45 and clinical stage IV of cervical cancer were significantly associated with cervical cancer, suggesting that CDC45 and clinical stage IV may be independent risk factors for the development of cervical cancer." (PMID 34557356, 2021). "To confirm the function of the CDC45 in cervical cancer, we performed single gene enrichment analysis by GSEA." (PMID 34557356, 2021). "Based on GEO and other multi-database biological big data mining, we found that CDC45 can be involved in the development of cervical cancer as an independent prognostic factor." (PMID 34557356, 2021). "Meanwhile, the relationship between the CDC45 expression and immune-infiltrating cells suggests that immunotherapy may facilitate the treatment of cervical cancer." (PMID 34557356, 2021). "Furthermore, univariate and multivariate cox regression analysis indicated that CDC45 and clinical stage IV were independent prognostic factors for cervical cancer." (PMID 34557356, 2021). "Finally, we confirmed the important role of CDC45 in the development and prognosis of cervical cancer." (PMID 34557356, 2021). "In addition, the HPA database validated the protein expression level of CDC45 in cervical cancer." (PMID 34557356, 2021). "Survival analysis was performed on the top 10 genes with protein-protein interactions showed that the overall survival (OS) time of CDC45, RFC4 and TOP2A was significantly correlated with the prognosis of cervical cancer." (PMID 34557356, 2021).